ITGB4 (integrin subunit beta 4)
Diseases named in the same sentence as ITGB4 in open-access papers (continued):
Sharing a sentence is not in itself a finding about the gene and the disease.
glioblastoma (7 papers, 2009 to 2024). The most malignant astrocytic tumor (WHO grade IV). "To investigate whether the expression levels of MGMT and NTN4/ITGB4 are associated in glioblastoma tissues, we analyzed the expression levels of primary tumors from The Cancer Genome Atlas - Glioblastoma multiforme (TCGA-GBM) repository." (PMID 24265816, 2013). "Correspondingly, compared with normal brain tissues, ITGB4 mRNA levels were upregulated in glioblastoma tissues." (PMID 30658712, 2019). "In glioblastoma, NTN4 is highly expressed at the tumor invading edge and promotes glioblastoma cell proliferation via ITGB4-Akt signaling." (PMID 30514230, 2018). "We report here that the suppression of either ITGB4 or NTN4 in glioblastoma cell lines significantly enhances cellular senescence." (PMID 24265816, 2013). "We find here that suppression of the expression of either ITGB4 or NTN4 in different glioblastoma cell lines leads to cellular senescence, consistently with the results from other ITGB4 silenced cell types." (PMID 24265816, 2013). "We have recently identified the interaction between netrin-4 (NTN4) and integrin beta-4 (ITGB4), which promotes glioblastoma cell proliferation via activating AKT-mTOR signaling pathway." (PMID 24265816, 2013). "In the current work we have explored the effect of NTN4/ITGB4 interaction on TMZ induced glioblastoma cell senescence." (PMID 24265816, 2013). "By Q-RT-PCR, we confirmed that both NTN4 and ITGB4 were expressed in all four analyzed glioblastoma cell lines, namely U251MG, U87MG, U118MG and T98G." (PMID 24265816, 2013). "To understand the effects of NTN4 and ITGB4 on glioblastoma cell senescence, we inhibited the expression of these two genes in U251MG cells by using short hairpin RNAs (shRNAs)." (PMID 24265816, 2013). "Current results suggest that NTN4/ITGB4 stimulated AKT activation provides glioblastoma cells with the ability of TMZ resistance." (PMID 24265816, 2013). "This suggests that the interaction between NTN4 and ITGB4 can regulate glioblastoma cell senescence." (PMID 24265816, 2013). "Therefore, the NTN4/ITGB4 transduced AKT activation possibly influences TMZ triggered glioblastoma cell senescence." (PMID 24265816, 2013). "However, for patients with relatively high expression of NTN4 and ITGB4 in glioblastoma tumors, the prevention of NTN4/ITGB4 interaction or concomitant use of the inhibitors of the AKT pathway may improve the therapeutic benefit of temozolomide." (PMID 24265816, 2013). "Here, we show for the first time that ITGB4 expression is increased in GSC and glioblastoma tissues." (PMID 30658712, 2019). "We have previously analyzed the expression of NTN4 and ITGB4 genes in the U251MG and U87MG glioblastoma cell lines." (PMID 24265816, 2013). "Our recent results reveal that glioblastoma tumors of most patients express low levels of NTN4 and high levels of ITGB4." (PMID 24265816, 2013). "Because NTN4/ITGB4 may together activate AKT, we investigated the role of this signaling pathway on the temozolomide resistance of glioblastoma cells." (PMID 24265816, 2013).
non-small cell lung carcinoma (7 papers, 2012 to 2026). A group of at least three distinct histological types of lung cancer, including non-small cell squamous cell carcinoma, adenocarcinoma, and large cell carcinoma. "ITGB4 overexpression can also lead to venous invasion and reduced overall survival in non-small cell lung cancer patients." (PMID 38172503, 2024). "Interestingly, expression of Itgb4 (integrin beta 4) was also increased in mouse lung tumor tissues as well as in human non-small cell lung cancer cell lines." (PMID 23285300, 2012).
bladder cancer (5 papers, 2021 to 2026). "Briefly, ITGB4 phosphorylation in bladder cancer tissues is associated with the activation of EGFR family signaling pathways involved in tumorigenesis and metastasis." (PMID 40252176, 2025). "Moreover, JUP has been found to downregulate ITGB4–43,489-ES through the glycosphingolipid biosynthetic pathway, which is also associated with prognosis of bladder cancer." (PMID 39132499, 2024). "Therefore, similar to our hypothesis, ITGB4 was associated with bone metastasis of bladder cancer and could be used as a prognostic marker in bladder cancer." (PMID 34402716, 2021). "Another study showed that ITGB4 redistribution facilitated tumor migration and invasion, making it a valuable prognostic marker for bladder cancer." (PMID 39132499, 2024). "Through multidimensional validation, we speculated that JUP regulating the ITGB4 − 43,489− ES might play a key role in bone metastasis and prognosis of bladder cancer through the glycosphingolipid biosynthesis ganglio series pathway." (PMID 34402716, 2021). "In bladder cancer patients with bone metastasis, JUP downregulates ITGB4 splicing events via the ganglio-series biosynthesis pathway, further supporting the role of GSLs in metastatic progression." (PMID 40252176, 2025). "Our analysis revealed that ITGB4/ITGA6 and ITGA5 were significantly downregulated with ISO treatment, suggesting that ISO may suppress cell migration and invasion of bladder cancer cells by decreasing integrin expression and activities." (PMID 38339062, 2024). "For bladder cancer patients with bone metastasis, JUP could down-regulating the ITGB4 − 43,489− ES by the pathway of glycosphingolipid biosynthesis ganglio series which was also related to the prognosis." (PMID 34402716, 2021).
junctional epidermolysis bullosa (5 papers, 2019 to 2025). "We report a 19-month-old boy with junctional epidermolysis bullosa carrying compound-heterozygous ITGB4 variants who fulfils the diagnostic criteria for JEB with pyloric atresia (JEB-PA); the pyloric atresia was surgically corrected in the neonatal period." (PMID 40918660, 2025). "Mutations in LAMA3, LAMC2, COL17A1, ITGA6, and ITGB4 are associated with the blistering skin disorder junctional epidermolysis bullosa and cause severe enamel hypoplasia, grooves and enamel pitting." (PMID 31417410, 2019). "ITGB4 inactivation results in pyloric atresia associated with junctional epidermolysis bullosa." (PMID 31242404, 2020). "Mutations in the ITGA6 or ITGB4 gene, encoding for the integrin α6β4 subunits result in the skin blistering disease junctional epidermolysis bullosa (JEB) associated with pyloric atresia (JEB-PA)." (PMID 32796709, 2020).
lung adenocarcinoma (5 papers, 2018 to 2026). A carcinoma that arises from the lung and is characterized by the presence of malignant glandular epithelial cells. "Furthermore, ITGB4 possesses diagnostic value for lung adenocarcinoma, demonstrating a significant correlation with overall survival." (PMID 39169946, 2024). "Additionally, ITGB4 serves as a pivotal gene for constructing a predictive risk model for the clinical prognosis of lung adenocarcinoma." (PMID 39169946, 2024). "For instance, Wang and colleagues recently reported a five-autophagy-related signature (ITGB4, NLRC4, ATG9B, CDKN2A, ERO1A) based on overall survival in patients with lung adenocarcinoma." (PMID 34252349, 2021).
melanoma (5 papers, 2018 to 2022). A malignant, usually aggressive tumor composed of atypical, neoplastic melanocytes. "In addition, a mutation in ITGB4 has been identified in a metastasis sample taken from acral melanoma patients." (PMID 34660316, 2021).
pancreatic adenocarcinoma (5 papers, 2012 to 2023). "ITGB4 has been proposed as a potential biomarker for pancreatic adenocarcinoma due to its overexpression and altered localization compared to normal and chronically inflamed pancreatic tissues." (PMID 36932441, 2023). "For this purpose, murine pancreatic adenocarcinoma cells Panc02 with or without stable ITGB4 KD were injected into WT or E-/P-selectin KO C57BL/6 mice." (PMID 36932441, 2023). "For example, cholangiocarcinoma (CHOL) overexpresses a large variety of subunits (e.g. ITGAV, ITGA1, ITGA4, ITGA5, ITGA11, ITGB1, ITGB2, ITGB6), whereas, the equally deadly pancreatic adenocarcinoma (PAAD) overexpresses a very limited set of integrins, including ITGA6 and ITGB4." (PMID 30046394, 2018).
cervical cancer (4 papers, 2017 to 2022). A primary or metastatic malignant neoplasm involving the cervix. "In cervical cancer, PD-L1 bound to β4 integrin (ITGB4) and directly affected genes associated with EMT and glucose metabolism through the ITGB4/SNAI1/SIRT3 signaling axis, highlighting a tumor-intrinsic role for PD-L1." (PMID 34065396, 2021). "High expression of PD-L1 and ITGB4 in human cervical carcinomas was significantly associated with lymph node metastasis and poor prognosis." (PMID 34065396, 2021). "Studies have shown that highly expressed PD-L1 in cervical carcinoma cells can promote the growth and metastasis of cervical cancer through the ITGB4/SNAI1/SIRT3 pathway." (PMID 36478746, 2022).
cholangiocarcinoma (4 papers, 2018 to 2025). A carcinoma that arises from the intrahepatic biliary tree (intrahepatic cholangiocarcinoma) or from the junction, or adjacent to the junction, of the right and left hepatic ducts (hilar cholangiocarcinoma). "Experimentally, ITGB4 knockdown markedly enhanced gemcitabine’s antiproliferative and pro-apoptotic effects on cholangiocarcinoma cells, supporting its role in mediating resistance." (PMID 40959663, 2025). "Collectively, these results indicate that ITGB4 may play a critical role in regulating gemcitabine sensitivity in cholangiocarcinoma cells, and its silencing enhances the antiproliferative and pro-apoptotic effects of gemcitabine." (PMID 40959663, 2025). "Furthermore, in our previous study, ITGB4 and ITGB6 mRNA levels in cholangiocarcinoma cell lines were high in HuCCT1; however, almost no expression of either molecule was observed in HuH28, which is known to grow slowly." (PMID 29584696, 2018).
liver cancer (4 papers, 2020 to 2024). An epithelial or non-epithelial malignant neoplasm that arises from the liver. "ITGB4 regulates the expression of transcription factor Slug to affect the epithelial-mesenchymal transition (EMT) of liver cancer cells, and promote tumor cell invasion." (PMID 38831335, 2024). "To determine the exact role of ITGB4 and ITGB7 in development of liver cancer, we used Si-ITGB4-4204 and Si-ITGB4-5690 to knockdown ITGB4, and Si-ITGB7-5402 and Si-ITGB7-5404 to knockdown ITGB7 gene in Bel-7402." (PMID 32127932, 2020). "In this paper, we used siRNA technology to knockdown ITGB4 and B7 to reveal their role in liver cancer." (PMID 32127932, 2020). "Si-ITGB4-4204 weakened liver cancer cells motility significantly, but Si-ITGB7-5404 enhanced liver cancer cells motility evidently." (PMID 32127932, 2020). "We found that ITGB4 and B7 affect the motility of liver cancer cells." (PMID 32127932, 2020). "Transwell assay results showed that Si-ITGB4-4204 weakened liver cancer cells motility significantly, but Si-ITGB7-5404 enhanced liver cancer cells motility evidently." (PMID 32127932, 2020). "Immunofluorescence results showed that knockdown of ITGB4 and ITGB7 can up-regulated the expression of E-cadherin/catenin complex on membrane of liver cancer cells." (PMID 32127932, 2020). "Immunofluorescence test showed that silencing ITGB4 and ITGB7 can increase the membrane expression of α-cateninin, β-catenin and E-cadherin in liver cancer cells to some extent." (PMID 32127932, 2020).
metastatic disease (4 papers, 2016 to 2022). "Analysis of Cetuximab-treated HNSCC patients suffering from recurrent metastatic disease showed that patients with low ITGB4 expression were at higher relative risk to have short PFS." (PMID 36076232, 2022).
prostate tumor (4 papers, 2014 to 2024). "Transgenic mice with a β4-integrin signaling domain mutation showed reduced prostate tumor formation and progression, thus supporting our data that ITGB4 is involved in tumor cell migration and metastasis." (PMID 24885350, 2014). "Through the regulation of ErbB2 and c-Met signals, ITGB4 promotes the self-renewal and transportation amplification of prostate tumor progenitor cells, as well as rapid proliferation of tumor cells." (PMID 39239559, 2024).
bipolar disorder (3 papers, 2018 to 2023). A disorder of the brain that causes unusual shifts in mood, energy, activity levels and the ability to carry out day-to-day tasks. "ITGB4, the index gene at the Aβ40TBS locus, encodes a transmembrane integrin involved in cell-to-cell adhesion, is differentially expressed in AD with potential roles in the blood-brain barrier, schizophrenia and bipolar disorder." (PMID 36609403, 2023).
head and neck cancer (3 papers, 2017 to 2023). A primary or metastatic malignant neoplasm affecting the head and neck. "In head and neck cancer, increased ITGB4 expression is associated with lymph node metastasis, distant metastasis, and increased mortality." (PMID 28084395, 2017). "COL1A1, ITGB4 and VTN have been associated with radioresistance in different types of cancer, such as nasopharyngeal carcinoma, esophageal squamous cell carcinoma and head and neck cancer." (PMID 34211843, 2021).
lymph node metastasis (3 papers, 2017 to 2022). "Studies have shown that high levels of ITGB4 expression are significantly correlated with the hallmarks of epithelial-mesenchymal transition, high tumor grade, and the presence of lymph node metastasis, and also exhibit an independent prognostic effect." (PMID 33362865, 2020). "Importantly, high PLEC levels and lymph node metastasis, Gleason score, PSA level, and metastasis all were positively correlated in double stratified ITGB4 or ITGA6 low, and PTEN low or PTEN copy loss number patients’ groups." (PMID 35773413, 2022).
oral squamous cell carcinoma (3 papers, 2013 to 2023). "However, the role of ITGB4 in oral squamous cell carcinoma (OSCC) remains unclear." (PMID 37371594, 2023).
pancreatic ductal adenocarcinoma (3 papers, 2024 to 2025). An infiltrating adenocarcinoma that arises from the epithelial cells of the pancreas. "In pancreatic ductal adenocarcinoma, ITGB4 promotes vimentin expression, induces EMT, and regulates migration and invasion." (PMID 39169946, 2024). "Overexpression of netrin-1 has been shown to impede the growth of pancreatic ductal adenocarcinoma cells by downregulating ITGB4 expression." (PMID 39169946, 2024). "Furthermore, ITGB4 overexpression promotes epithelial-mesenchymal transition in pancreatic ductal adenocarcinoma." (PMID 39152432, 2024).
acute lung injury (2 papers, 2022 to 2024). A condition of lung damage that is characterized by bilateral pulmonary infiltrates (pulmonary edema) rich in neutrophils, and in the absence of clinical heart failure. "Integrins play an important role in regulating vascular permeability; in particular, Itgb1 and Itgb4 have been shown to protect from vascular leakage in acute lung injury." (PMID 39513364, 2024). "Separately, we have characterized the role of ITGB4 as a mediator of lung vascular permeability and inflammatory responses in acute lung injury (ALI) models." (PMID 35250607, 2022).
allergic asthma (2 papers, 2012 to 2022). A asthma with a basis in a pathological type I hypersensitivity reaction. "Overall, this study suggested that downregulation of ITGB4 expression in airway epithelial cells could impair the antigen presentation ability of these cells, which further regulate airway inflammation reaction in allergic asthma." (PMID 22545078, 2012).
aplasia cutis congenita (2 papers, 2021 to 2022). Aplasia cutis congenita (ACC) is a rare skin disorder characterized by localized absence of skin that is usually located on the scalp but can occur anywhere on the body including the face, trunk and extremities. "Both patients had aplasia cutis congenita; PT24 with ITGB4 mutations also had pyloric atresia." (PMID 36578049, 2022).
atherosclerosis (2 papers, 2022 to 2025). A disease characterized by the build-up of fatty material and calcium deposition in the arterial wall resulting in partial or complete occlusion of the arterial lumen. "Genetic elements are of importance for the elevated risk of atherosclerosis and many genes have been implicated in the initiation and progression of atherosclerosis, including integrin beta 4 (ITGB4), intercellular adhesion molecule-1 (ICAM-1), and natriuretic peptide receptor 1 (NPR1)." (PMID 36293483, 2022). "ITGB4 is indispensable for adhesion, proliferation, apoptosis, and senescence, which are important factors in the development of atherosclerosis." (PMID 36293483, 2022). "In conclusion, our findings demonstrate that NPR1 deficiency increases vascular endothelial cell adhesion by stimulating ITGB4 expression, which may contribute to the development of atherosclerosis." (PMID 36293483, 2022). "Additionally, a reduced NPR1 and an increased ITGB4 expression level were found in an atherosclerosis mouse model." (PMID 36293483, 2022). "Thus, we further examined the expression of NPR1 and ITGB4 in the aorta from a mouse model of atherosclerosis." (PMID 36293483, 2022). "An elevated ITGB4 level has been found in mice with atherosclerosis." (PMID 36293483, 2022). "In atherosclerosis, ECs communicated extensively with pericyte cells and SMCs through LAMININ (LAMA5-(ITGA1+ITGB1), LAMA5-(ITGA7+ITGB1), LAMB2-(ITGA6+ITGB4), LAMB2-(ITGA6+ITGB1)) and COLLAGEN (COL4A1-(ITGA1+ITGB1), COL4A2-(ITGA1+ITGB1)) pathways." (PMID 40225569, 2025). "Furthermore, the atherosclerosis mouse model displays a decreased NPR1 and an increased ITGB4 expression." (PMID 36293483, 2022).
Breast Invasive Carcinoma (2 papers, 2023 to 2024). "According to the same dataset (Breast Invasive Carcinoma, TCGA PanCancer Atlas, 1082 samples), ITGB4, previously characterized as a negative prognosticator associated with the basal-like subtype, is the beta-family integrin best correlating with FOSL1 expression level." (PMID 37176013, 2023).
clear cell renal cell carcinoma (2 papers, 2022). "Integrin β4 (ITGB4) participates in tumorigenesis and progression of several malignancies, but its role and related mechanisms in clear cell renal cell carcinoma (ccRCC) remain unclear." (PMID 35305660, 2022). "Knockdown of METTL14 promotes ITGB4 expression via m6A-YTHDF2, stimulates EMT, and promotes migration, invasion, and metastasis in renal clear cell carcinoma cells." (PMID 36358640, 2022).
depression (2 papers, 2018 to 2022). "For AQP1 and ITGB4, studied only in rodent models of depression, the present study was the first to implicate them in human suicidal behavior." (PMID 35806070, 2022).
epidermolysis bullosa simplex (2 papers, 2021 to 2026). Epidermolysis bullosa simplex (EBS) is a group of hereditary epidermolysis bullosa (HEB) disorders characterized by skin fragility resulting in intraepidermal blisters and erosions that occur either spontaneously or after physical trauma. "ITGB4 was involved in epidermolysis bullosa simplex (FDR = 0.008169)." (PMID 34545326, 2021).